CRP (C-reactive protein)
Diseases named in the same sentence as CRP in open-access papers (continued):
Sharing a sentence is not in itself a finding about the gene and the disease.
Obesity (continued). "This expression of CRP indicates a link between chronic inflammation and obesity." (PMID 36381804, 2022). "One such mechanism may involve the obesity-related state of chronic low-grade inflammation, as indicated by biomarkers such as c-reactive protein (CRP) and interleukin-6 (IL-6)." (PMID 35301057, 2022). "Previous investigations revealed a significant relationship between CRP and obesity." (PMID 35996695, 2022). "In addition, the association was more noticeable among the older group (≥50 years), and the combination of CRP levels with obesity and hypertension led to increased incidence of T2DM." (PMID 35620114, 2022). "Obesity, especially subcutaneous adiposity, is the key correlate of CRP levels in women." (PMID 35927639, 2022). "Previous cross-sectional studies have shown that CRP correlates with obesity indicators such as BMI, WHR, and adiposity; some authors even suggest that the fat mass has a greater ability to classify subjects with high CRP serum levels compared with BMI and WHR." (PMID 35407457, 2022). "This high prevalence of obesity may result in CRP elevation in urban areas in SSA and among SSA migrants in Europe." (PMID 34478414, 2022). "Both drugs have proven to be effective in reducing inflammation through various pathways: they reduced CRP levels in patients with obesity, while colchicine was also effective in reducing IL‐6, IL‐16, resistin, complement proteins C5a and C9, and the activity of the COX‐2 enzyme." (PMID 35837843, 2022). "The key findings of the current study were the significant interaction result of CETP rs708272 polymorphism with DIL and DII on obesity indices (WC and BMI), lipid profiles (TG, HDL, LDL/HDL), inflammatory markers (IL-18, CRP, and PGF2α), and antioxidant markers (TAC and SOD) in T2DM patients." (PMID 34354158, 2021). "The association between obesity and pulmonary function no longer existed after additional adjustment for insulin resistance or C-reactive protein (CRP)." (PMID 34272443, 2021). "The increase in obesity-related PROs and CRP levels may therefore result in a higher score of the composite indices to measure disease activity." (PMID 34527685, 2021). "While many studies associating periodontal diseases with higher serum CRP levels do not measure or control BMI, obesity and overweight were adjusted and not excluded from our study because of their relevance and weight on external validity." (PMID 34439905, 2021). "Obesity independently elevates inflammatory markers such as CRP." (PMID 34436472, 2021). "The hypothesis of this study is that individuals with obesity are more likely to have elevated leptin levels and inflammatory markers (including CRP, IL‐6, TNF‐α)." (PMID 33680494, 2021). "However, inflammation status as a potentially important link between obesity and FLD and the specific mediation role or effect of key inflammatory biomarkers (hs-CRP, TNF-α and APN) between the association of obesity and FLD have not been explored." (PMID 34571772, 2021). "Our data do not support a link of inflammation (as determined by TNFα, IL‐6, procalcitonin and CRP values) to BCAA concentrations, thus the mechanisms underlying increased BCAA levels in obesity remain unclear." (PMID 33058486, 2021). "Moreover, like insulin resistance, obesity was associated with lower FEV1, FVC and higher FEV1/FVC ratio only in the highest CRP tertile." (PMID 34272443, 2021). "Most studies investigating the role of inflammation in obesity have used CRP and/or IL-6." (PMID 33604566, 2021). "∆hs-CRP was the only factor among three parameters we examined (∆triglycerides, ∆hs-CRP, and ∆HOMA-IR) that showed association with variations in serum FT levels during the lifestyle intervention in women with obesity." (PMID 34575354, 2021). "There is also evidence that serum CRP levels may also be significantly elevated in diseases involving chronic inflammation such as chronic pancreatitis, polycystic ovarian syndrome, obesity and cancer." (PMID 34488637, 2021).
Obesity (continued). "Reported results have demonstrated that older age, comorbidities, obesity, and laboratory abnormalities including impairment of oxygen, elevated CRP concentration, higher D-dimer level, and increased serum ferritin were associated with severe illness or mortality 14-17." (PMID 33456349, 2021). "Surprisingly, although CRP levels were elevated with obesity, they decreased between T1 and T3." (PMID 34195568, 2021). "Our data demonstrate a strong negative association of IGFBP-1 with overweight/obesity, and the inflammatory marker Hs-CRP." (PMID 34394011, 2021). "Growing scientific evidence shows obesity-related conditions such as insulin resistance, type 2 diabetes, and the metabolic syndrome as well as obesity-related systemic markers (e.g., leptin, adiponectin, SHBG, insulin and the IGF axis and C-reactive protein) are associated with breast cancer." (PMID 34066392, 2021). "The infiltration of expanded adipose tissue by macrophages, which are responsible for both the generation of inflammatory signals and the production of cytokines such as IL-6 and TNF-α, could explain the rise in CRP in obesity." (PMID 34680097, 2021). "Of note, TSH and CRP levels were higher in patients with obesity III." (PMID 34578857, 2021). "BMI (or obesity for that matter) was associated with higher CRP mainly in females and to a lesser extent also in males (not shown)." (PMID 32827080, 2021). "Furthermore, the HF diet-induced obesity led to the higher plasma inflammation demonstrated by an increased level of CRP." (PMID 34158075, 2021). "In both genders, C-reactive protein increased with the increase in all obesity indices." (PMID 33914792, 2021). "Second, the association between obesity and pulmonary function no longer existed after additional adjustment for insulin resistance or CRP." (PMID 34272443, 2021). "Furthermore, the HF diet-induced obesity led to a significant increase of C-reactive protein (CRP), the inflammation marker, in the fasting plasma of 11-month-old animals, when compared to the St diet-fed animals." (PMID 34158075, 2021). "However, the CRP value is affected by many factors, for instance, inflammation caused by injury, infection, and autoimmune diseases can lead to increased (serum) CRP levels; other factors, including smoking and obesity, can also lead to high levels of CRP." (PMID 33740937, 2021). "However, a negative correlation was observed between telomere length and age, as expected, and the obesity indices BMI and WC and the inflammatory biomarkers CRP and homocysteine." (PMID 34769797, 2021). "Considering that obesity is one of the main determinants of chronic low-grade inflammation in the general population, the relationship between CRP and many phenotypes may be confounded by the effects of obesity." (PMID 34386016, 2021). "However, in accordance with our results, in 22 patients with obesity and impaired glucose homeostasis, CRP and IL-6 levels decreased 1 month and 6 months after SG13." (PMID 34108550, 2021). "A recent meta-analysis of nine studies demonstrated that a decreasing trend in CRP levels was seen when adults with various chronic conditions (e.g., chronic obstructive pulmonary disorder) and diseases (e.g., cardiovascular and obesity) consumed >20 g of whey protein daily." (PMID 34068841, 2021). "Elevated CRP, symptomatic of obesity, may signify an overproduction of proinflammatory cytokines that directly impinge on the insulin signal transduction pathway." (PMID 34769939, 2021). "Moreover, in non-diabetic patients with amnestic MCI co-occurring with overweight or obesity, metformin appeared to ameliorate systemic inflammation lowering CRP levels and a partial improvement in recall memory." (PMID 33967682, 2021). "Importantly, obesity-induced metabolic inflammation produces CRP, as a proinflammatory biomarker, and adipokines, including tumor necrosis factor-alpha (TNF-α) and interleukin (IL)-6, which further propagate inflammation." (PMID 34055004, 2021).
Obesity (continued). "In obesity, the impact of muscle strength, a proxy to characterize general health, exhibited a stronger effect and showed a negative association with CRP levels." (PMID 32827080, 2021). "Besides adipokines, pro-inflammatory markers TNF-alpha and CRP have been shown to be disturbed in chronic diseases such as obesity and impaired glucoregulation." (PMID 33540682, 2021). "Thus, there were systemic contributions from obesity and local contributions from periodontitis to CRP blood levels indicating systemic inflammation." (PMID 32827080, 2021). "This led Gonzalez to hypothesize that CRP elevations attributable to PCOS may be obscured in the presence of obesity." (PMID 33800490, 2021). "Léger's and LM-LBM equations indicated a higher prevalence of central obesity, general overweight/obesity or obesity, elevated fasting insulin, and CRP levels and low HDL-C in females at the upper tails of eGFR distributions compared with those on the lower ones." (PMID 34778125, 2021). "Obesity and IR are considered the main predictive factors of increased CRP." (PMID 35053629, 2021). "The inflammation caused by overnutrition or obesity is characterized by the activation of various immune cells, which release pro-inflammatory cytokines, such as tumor necrosis-alpha (TNF-α), interleukin-6 (IL-6), and C-reactive protein (CRP)." (PMID 34867458, 2021). "Further studies are needed to explore the mediator role of hs-CRP on obesity by race/ethnicity." (PMID 34065158, 2021). "A third possible mechanism is that in addition to the association between obesity and low FEV1, low FVC, and high FEV1/FVC ratio, it may also be associated with a higher level of C-reactive protein (CRP)." (PMID 34836307, 2021). "Nevertheless, our findings show that %BF may serve as an indicator for obesity‐related increase of CRP release and insulin resistance in the study population." (PMID 33680494, 2021). "In addition to these analytes, and as previously reported, pregravid obesity resulted in significantly higher levels of IL-6 and CRP both at T1 and T3, highlighting a state of chronic low-grade inflammation." (PMID 34195568, 2021). "Our results demonstrated that the levels of CRP, mediator of inflammation, is increased in obesity." (PMID 34625635, 2021). "We also found the most potent genetic correlation between CRP and obesity in the UK Biobank and Endocrine, nutritional and metabolic diseases in the FinnGen cohort (obesity belongs to the endocrine, nutritional and metabolic diseases according to the ICD-10 tree)." (PMID 34386016, 2021). "In the current study, sarcopenia was an independent risk factor for MetS regardless of age, sex, obesity, DM, HT, DL, smoking, alcohol intake and CRP levels." (PMID 33739984, 2021). "Sex, obesity, malnutrition risk, CRP, renal function, and smoking status, while not statistically significant, were included in the final model due to the a priori selection criteria." (PMID 33806205, 2021). "These authors reported that obesity was associated with heightened systemic inflammation, as noted by increases in plasma IL-6, IL-17, C-reactive protein (CRP), and prostaglandin E2 (PGE2)." (PMID 34421889, 2021). "Our results are in line with these studies, supporting the concept that obesity may falsely increase the levels of CRP in RA patients with low disease activity, giving elevated rates of disease activity in those patients." (PMID 34721412, 2021). "Although high IL-6 in COVID-19 infection has a prominent role in inflammation linked mortality, recent studies showed that colchicine treatment decreased the concentrations of multiple inflammatory molecules, including IL-6, CRP, and resistin in patient with obesity." (PMID 34220807, 2021). "In contrast, an inflammatory state might be the consequence of micronutrient malnutrition: vitamin D deficiency is associated with a high prevalence of inflammation and vitamin D supplementation slightly reduced CRP levels in individuals with obesity." (PMID 33026590, 2021).
Obesity (continued). "Moreover, subjects with obesity had significantly higher C-reactive protein (CRP) and TNFα-R1 and reduced SHBG and adiponectin plasma levels compared to the normal-weight controls." (PMID 33689083, 2021). "It has been suggested that CRP (and high sensitivity CRP) is an obesity independent marker of NASH." (PMID 33203036, 2020). "Moreover, CRP levels predict obesity after 1–6 years of follow-up, providing a potential therapy goal in short-term treatment." (PMID 32154197, 2020). "The lack of associations between CRP and comorbidity is known from other studies in subjects with obesity, which contrasts to findings in the general population." (PMID 32646381, 2020). "Adjustment variables for multivariable-adjusted HRs included main covariates (age, sex, SBP, HbA1c, LDL-C, HOMA-IR, CRP, eGFR and use of antihypertensive medication) and obesity categorized by (a) BMI (≥27.5) or (b) waist circumference (WC ≥ 90 cm for men, ≥85 cm for women)." (PMID 32238873, 2020). "The increase of adiposity might be an essential factor in expression of CRP and chronic inflammation leading to obesity, which needs to be further explored." (PMID 32154244, 2020). "The association between low CRP and E4 observed in this study is in accordance with other studies in subjects with and without obesity." (PMID 32646381, 2020). "CRP was strongly associated with obesity (OR = 5.36, 95th% CI 2.45–11.73, p < 0.002) but not to an interaction of obesity with GERD." (PMID 32625121, 2020). "Moreover, 63% of their participants simultaneously suffered from HTN, DM, hypercholesterolemia and obesity had higher levels of hs-CRP, mean of at least 1.80 mg/l." (PMID 32489776, 2020). "Chronic inflammation happens through frequent stress factors such as poor diet and obesity and it is recognized with high levels of serum inflammatory biomarkers including high sensitivity C-reactive protein (hs-CRP), interleukin (IL)-6, and tumor necrosis factor-α (TNF-α)." (PMID 33117453, 2020). "Elevated concentrations of C-reactive protein have been seen in adults with exposure to stress associated with socioeconomic disadvantages, and there is a confirmed link between CRP and obesity." (PMID 31728932, 2020). "Other mediators included insulin resistance, CRP, and obesity." (PMID 33148273, 2020). "Moreover, in adults (aged 45–84 years), in a population study of 6,814 participants with a median follow-up time of four years, found that inflammatory markers (IL-6 and CRP) are independent predictors of heart failure from obesity." (PMID 33299523, 2020). "In addition, urine excretion of enterolignans has been inversely associated with C-reactive protein (CRP) levels and metabolic syndrome components, such as type 2 diabetes (T2D) and obesity." (PMID 32987732, 2020). "IC training caused a significant decrease in CRP concentration in women with obesity, but CRP levels in this group were still higher than in normal-weight women." (PMID 33255278, 2020). "Previously, obesity and hormone therapy use were reported as determinants of high CRP level." (PMID 32397288, 2020). "Increased serum levels of C-reactive protein (CRP) are a marker of chronic inflammation in obesity." (PMID 33183332, 2020). "For gene-obesity interaction, obese individuals carrying the minor-minor genotype of CRP SNP rs1130864 and rs3093059 had a significantly lower adjusted mean IMT value than those carrying minor-major/major-major genotype (0.70 [0.64, 0.76] and 0.64 [0.56, 0.75], respectively)." (PMID 32214403, 2020). "In summary, long-term CRP elevation can lead to adult-onset obesity." (PMID 32154244, 2020). "There was no observed association between markers of obesity (BMI, insulin, leptin, and CRP), serum 25-OH vitamin D levels and estradiol or estrone levels." (PMID 32566743, 2020). "Furthermore, a low-grade, chronic inflammation develops with aging and obesity, as indicated by higher circulating concentrations of C-reactive protein (CRP) and interleukin 6 (IL-6)." (PMID 31963377, 2020).
Obesity (continued). "Hence, considering the public health burden of both obesity and elevated hs-CRP levels, obesity-targeted prevention and management strategies are warranted to prevent and ameliorate future inflammation and risk of CVD." (PMID 33182500, 2020). "CRP and sVCAM-1 levels were increased among the three obesity groups." (PMID 32893859, 2020). "Blood CRP levels in populations of ostensibly healthy people have a positively skewed log-normal distribution, and baseline blood CRP levels in individuals can vary with age, sex, race, genetics, and obesity." (PMID 33633738, 2020). "On the other hand, Ramdas and Jella reported that higher BMI is associated with higher CRP concentrations, pointing to that the levels of CRP were within the normal ranges till class I obesity individuals while class II and III subjects exhibit elevated level of CRP." (PMID 32893859, 2020). "However, there are few large-scale and no nationally representative studies assessing elevated levels of CRP and measures of overweight and obesity in sub-Saharan African populations." (PMID 33141863, 2020). "The results of the present study indicate that CRP-derived PVAT may play a role in the pathogenesis of neointimal hyperplasia after angioplasty in obesity." (PMID 32046736, 2020). "To conclude, we demonstrated that higher BMI, overweight/obesity and diagnosis of FEP were significantly associated with lower regional GM volumes and that dyslipidemia and elevated CRP could contribute to obesity related neurostructural alterations." (PMID 33173508, 2020). "The participants recruited for the current study were men with overweight/obesity who also had an elevated waist circumference and had ≥1 other CVD risk factor (elevated LDL cholesterol and TGs, reduced HDL cholesterol, elevated CRP, elevated blood pressure, or elevated fasting glucose)." (PMID 32211803, 2020). "CRP is a marker of general low-grade inflammation and high levels of this marker are common in adolescents, in parallel with the increasing prevalence of obesity and metabolic syndrome." (PMID 32751389, 2020). "C-reactive protein (CRP) is a sensitive measure of inflammation but lacks disease specificity for joint inflammation and elevated levels are seen in intercurrent illness or with obesity." (PMID 33292827, 2020). "However, significantly higher values were found for CRP, waist circumference, BMI, obesity rate for NCEP-ATPIII criteria, VASI and VIDA scores in the non-segmental vitiligo patients (0.001, <0.001, 0.001, 0.05, <0.001 and <0.001, respectively)." (PMID 32113676, 2020). "Moreover, CRP can be stimulated by leptin levels and CRP seemed to bind leptin receptor exerting modulations in both adipose tissue physiology as well as pathogenesis of obesity-related diseases." (PMID 32610476, 2020). "Patients with obesity reportedly have chronic inflammation due to sustained production of proinflammatory cytokines in adipose tissue and higher levels of inflammatory cytokines, such as IL-6, CRP, and certain adipokines." (PMID 33326480, 2020). "Smoking as well as obesity and CVD have been associated with elevated CRP and fibrinogen levels." (PMID 33173057, 2020). "Moreover, patients with obesity exhibited increased circulating levels of markers of systemic inflammation, including C-reactive protein (CRP), fibrinogen, von Willebrand factor, or TNF-α (all p < 0.05), regardless of insulin resistance." (PMID 32512939, 2020). "We tested the hypothesis CRP derived from PVAT in obesity contributes to vascular remodeling after injury." (PMID 32046736, 2020). "In multivariable model, there was a significant association between high pre-RT CRP and RT-related pain (OR = 2.44, 95% CI = 1.02, 5.85) regardless of obesity status." (PMID 31138314, 2019). "In addition, other variables that can alter the levels of CRP, such as obesity and smoking, were exclusion criteria for the study." (PMID 31411315, 2019).